FANCL (FA complementation group L)
Diseases named in the same sentence as FANCL in open-access papers (continued):
Sharing a sentence is not in itself a finding about the gene and the disease.
cancer (17 papers, 2010 to 2025). A tumor composed of atypical neoplastic, often pleomorphic cells that invade other tissues. "We find that the FANCL cancer-associated mutations I136V, L154S, W212A and L214A, R221W, R221C, and V287G destabilize the FANCL protein by disrupting the protein fold." (PMID 32420600, 2020). "For example, in one study 3.8% of patient samples were found to have missense mutations in FANCL across various cancer types." (PMID 32420600, 2020). "Whole genome sequencing studies of cancer cells from patients identified point mutations in the FANCL URD domain." (PMID 32420600, 2020). "This mutation has a strong negative impact of the function of FANCL, and the sequencing of the cancer cells revealed only 138 other mutations, indicating that the R221W mutation in FANCL could have contributed to the progression of the cancer." (PMID 32420600, 2020). "The cancer-associated mutations that cause a defect in the function of FANCL could have contributed to the progression of cancer in patients, and highlights residues important for the function of FANCL." (PMID 32420600, 2020). "Other cancer-related genes and biological processes are enriched in accelerated genomic regions of elephants including FANCL and TNF-mediated signaling pathway." (PMID 36797268, 2023). "The mutations I136V, L154S, W212A and L214A, R221W, R221C, and V287G are found to destabilize the fold of FANCL, which would therefore reduce the amount of active FANCL in cancer cells." (PMID 32420600, 2020). "In this study, we aimed to investigate the differences in ICL repair via the FA pathway, including the function of FANCL, as well as the DNA damage responses to ICLs between elephants and humans as a step toward understanding their unique cancer resistance mechanisms." (PMID 40708996, 2025). "Based on these findings, we hypothesized that the characteristics of FANCL, along with the FA pathway and DNA damage responses to ICLs, contribute to cancer resistance mechanisms in elephants." (PMID 40708996, 2025). "Mutations have been found in FANCL in non-FA patients’ cancer cells through whole genome sequencing studies." (PMID 32420600, 2020). "Here, we characterized mutations in the FANCL URD domain to determine whether they affect the function of FANCL, and whether they could be responsible for the progression of cancer in these patients." (PMID 32420600, 2020). "This hypothesis is supported by the signature of positive selection of some FA/BRCA components (BRCA2, FANCA, FANCE, and FANCL) identified in long-lived and cancer-resistant species." (PMID 30487452, 2018). "The decreased activity of FANCL with these mutations could contribute to the progression of cancer in non-FA patients by decreasing genomic stability." (PMID 32420600, 2020). "Interestingly, some mutations in FA genes, such as FANCL, which have been observed in patients’ cancer cells have not been found in FA patients." (PMID 32420600, 2020). "These mutations which affect the fold and activity of FANCL may contribute to tumorigenesis in these non-FA cancer patients, and this implicates FA genes in general cancer progression." (PMID 32420600, 2020). "For instance, in vitro reconstitution of E1, E2/FANCT, E3/FANCL cascades has been successful in finding two hits that reduce FANCD2 foci formation and synergize with carboplatin for cancer cell killing." (PMID 32190289, 2020). "A panel of eight cancer driver genes (CCNE1, TPX2, ELF3, FANCL, JAK2, GSK3B, CEP76, and SYK) were differentially expressed in recurrent TNBCs, and were also overexpressed in TCGA and METABRIC." (PMID 30665374, 2019).
tumor (15 papers, 2013 to 2026). "Contrarily, a pathogenic CHEK2 variant was detected in a patient with a GI-negative tumor, while a patient’s tumor with an inconclusive GI status harbored a likely pathogenic FANCL variant and a splice variant in ATM." (PMID 38067228, 2023). "The specific HRR mutations identified in the 21 tumour samples were: BRIP1 (n = 5), CDK12 (n = 3), RAD54L (n = 2), RAD51B (n = 2), RAD54L rearr (n = 1), ATM rearr (n = 1), FANCA rearr (n = 1), FANCD2 (n = 1), FANCL rearr (n = 1), FANCL (n = 1), RAD51C (n = 1), RAD52 del (n = 1), XRCC3 rearr (n = 1)." (PMID 30353044, 2018). "These included genes with homologs involved in tumor suppression (OPCML), cell growth regulation (CDKL3), DNA repair (FANCL), and innate immunity (TMED7-TICAM2)." (PMID 30845962, 2019). "For example, in the PROfound trial, 145 patients with a tumor BRCA2 alteration were randomized while no patients with a tumor FANCL or RAD51C alteration were randomized." (PMID 35768576, 2022). "Among the multiple phenotypes identified for the clinical presentation of FA, patients with FAAAP100, FANCB, or FANCL mutations may be best classified as having a high multiple congenital anomaly (MCA), low neoplasia phenotype due to impaired ICL repair rather than homologous recombination repair." (PMID 40232843, 2025). "Inhibition of FA signalling components—such as FANCL, UBE2T or FANCD2—has been shown to sensitise tumour cells to crosslinking agents without inducing catastrophic genomic instability." (PMID 41486508, 2026). "In our earlier studies, we discovered that a new form of FANCL protein, named FAVL, dysregulates the FA signaling in non-FA human tumor cells and acts as a tumor promoting factor by inactivating FANCD2 and FANCI/the ID complex." (PMID 34884777, 2021).
genetic disease (1 paper, 2021). "Finally, the most intriguing case is represented by discovering an HKO for the FANCL gene, which, when mutated, causes FA, a severe genetic disease often lethal in childhood." (PMID 33727708, 2021).
FANCL also shares sentences with these, for which no sentence is quoted: ovarian carcinoma (3 papers); lymphoma (2); acute myeloid leukemia (1); astrocytoma (1); atypical teratoid rhabdoid tumor (1); bladder cancer (1); bowel cancer (1); breast tumors (1); cervical cancer (1); cervical tumor (1); colorectal cancer (1); ependymoma (1); Fanconi anemia complementation group L (1); focal epilepsy (1); hematopoietic disease (1); hypogonadism (1); Lafora disease (1); leukemia (1); lung carcinoma (1); Lynch syndrome (1); neuroblastoma (1); Obesity (1); osteosarcoma (1); ovarian failure (1); pancreatitis (1); parasitemia (1); Premature ovarian insufficiency (1); prostate carcinoma (1); retinoblastoma (1); rhabdomyosarcoma (1).
A further 1 disease shares a sentence with FANCL in 1 paper.